BRAF (B-Raf proto-oncogene, serine/threonine kinase)
Diseases named in the same sentence as BRAF in open-access papers (continued):
Sharing a sentence is not in itself a finding about the gene and the disease.
cancer (continued). "Considering the intricate signaling biology of CRAF in the MAPK-dependent and MAPK-independent pathways, the diverse spectrum of alterations in CRAF and BRAF detected in cancer can manifest distinct functional attributes." (PMID 38111008, 2023). "For example, KRAS is responsible for most RAS-driven cancers, and BRAF has the highest basal activity among RAF isoforms." (PMID 38150000, 2023). "It activates the MAPK pathway and promotes cancer cell proliferation, making BRAF an excellent target for anti-cancer therapy." (PMID 38136350, 2023). "BRAF is a receptor protein that plays a role in cell survival and proliferation, and aberrant activation has been related to the onset and spread of cancer." (PMID 37885828, 2023). "Here, we reported that BRAF/VEGFA targeting influenced monocyte‐derived macrophages infiltration through a cancer‐derived signal." (PMID 37183363, 2023). "Research statistics show that over 85% of cancers have overactive MAPK signaling, which is directly caused by genetic changes in its upstream activators or key molecules (including RTK, RAS, and BRAF) or affected by changes in other regulatory genes." (PMID 36969076, 2023). "Nevertheless, the ability to specifically degrade BRAF V600E provides a convenient tool for probing the role of BRAF V600E in driving the proliferation of several heterozygous BRAF V600E-harboring cancer cell lines." (PMID 38136350, 2023). "Alterations in genes such as the FGFR, HER2, IDH1, and BRAF, result in cancer development, growth, and proliferation." (PMID 37046631, 2023). "While rare in general, in-frame deletions within BRAF exon 12 have been reported in a small number of human cancer subtypes, the majority of which eliminate the region extending from amino acid residue N486 to P490 (termed ∆NVTAP)." (PMID 37079639, 2023). "Another GST, GSTP1, increased autocrine growth on cancers with Kirsten rat sarcoma viral oncogene homologue (KRAS) and B-raf proto-oncogene serine/threonine kinase (BRAF) mutations." (PMID 36978808, 2023). "In human cancers, the ∆NVTAP variant exhibits MAPK pathway signaling activity comparable to that of BRAF V600E." (PMID 37079639, 2023). "EGFR (epidermal growth factor receptor) and BRAF (B-Raf proto-oncogene, serine/threonine kinase) are both well-studied kinases that play crucial roles in cancer progression." (PMID 37240450, 2023). "Mutant BRAF is often the underlying cause of various types of cancer and mutant RAS, the upstream regulator of BRAF, is a driver of up to one-third of all cancers." (PMID 38150000, 2023). "RAS, a small GTPase protein that acts upstream of BRAF, has been identified as a driver of up to one-third of all cancers." (PMID 37163002, 2023). "Our results showed that SJ-C1044 impaired the growth of all KRAS and BRAF mutant cancer cells, with IC50 values ranging from 160 to 628 nM." (PMID 37504287, 2023). "A multiplex analysis on conditioned media from cancer cells confirmed that cytokines were upregulated by BRAF V600E and that treatment with vemurafenib (a specific BRAFi) reverted this increase." (PMID 37627054, 2023). "This basket trial demonstrated that dabrafenib and trametinib significantly improved long-term survival in patients with BRAF V600E-mutant anaplastic thyroid cancer, representing a meaningful treatment option for this rare and aggressive cancer type." (PMID 37185413, 2023). "In this Chinese PDAC cohort, KRAS mutations were mutually exclusive with P/LP alterations in BRAF, CTNNB1, ELF3, FGF19, and other cancer‐related genes." (PMID 36999792, 2023). "Accordingly, pre-clinical and clinical studies designed to explore the benefits of combined BRAF inhibitors and drugs targeting the ezrin-regulated actin cytoskeleton as a novel therapeutic approach for BRAFV600E-mutated cancers should be encouraged." (PMID 37629086, 2023).
cancer (continued). "Finding BRAF mutations or PPARG, NTRK1, NTRK3 and ALK fusions were strong predictors of a higher risk of cancer (approaching 100%) while other mutations like RAS, PTEN and EIF1AX or THADA fusions were associated with a significant but lower risk of cancer." (PMID 37510219, 2023). "Right-sided and left-sided CRCs exhibit distinct underlying biological features, with a higher occurrence of MSI-high, CIMP-high, and BRAF mutant cancers observed among right-sided CRCs." (PMID 37865754, 2023). "Some variants, including BRAF V600E, the copy number variation of ERBB2, PTEN A121E and R161*, are associated with >10 cancer indications and form hubs of the network." (PMID 36856726, 2023). "The effects of BRAF degradation on cell viability divide BRAF V600E-harboring cancer cells into two broad categories: those killed by BRAF V600E degradation and those whose viability is only partially inhibited." (PMID 38136350, 2023). "Unfortunately, the emergence of acquired resistance to BRAF inhibitors (BRAFi) was inevitable and is one of the main reasons for therapy failure in BRAF-mutant cancers." (PMID 36694209, 2023). "A highly specific and comparable diagnostic approach is available using the monoclonal antibody ‘VE1’ for detection of BRAF p.V600E in human cancer." (PMID 37901104, 2023). "The ROAR study has provided evidence for the pan-cancer efficacy of the BRAF and MEK inhibitor combination in 21 histologies." (PMID 38001751, 2023). "The selective cytotoxicity observed in KRAS-mutant and BRAF-mutant cancer cells further supports the potential therapeutic utility of SJ-C1044 in targeting specific oncogenic mutations." (PMID 37504287, 2023). "Such tumors remain microsatellite-stable, suggesting that other factors can influence the MSI phenotype in BRAF-positive cancer." (PMID 37190216, 2023). "We analyzed the human‐specific and mouse‐specific mRNAs differentially expressed after BRAF/VEGFA targeting in order to identify intercellular signals between cancer and stromal cells." (PMID 37183363, 2023). "To explore this goal, we employed PK5L1940 and BRAF cancer cells to compare results in both KRAS and BRAF mutant models in RAG1 KO mice." (PMID 37415974, 2023). "In recent years, increasing evidence has suggested that combining immune checkpoint inhibitors (ICIs) and BRAF/MEK inhibitors can enhance the efficacy of cancer treatment, especially for patients who are resistant to monotherapy of ICIs." (PMID 38111008, 2023). "In contrast, dual inactivation of DUSP4 and DUSP6 selectively impairs growth in NRAS and BRAF mutant cells in cancer through hyperactivation of MAPK signaling." (PMID 37026010, 2023). "Oncolytic virotherapy with various viruses has been shown to induce the antitumor effect against KRAS/BRAF-mutant cancers, including CRC." (PMID 37972012, 2023). "Following the discovery of BRAF mutations in human cancers in 2002, Tamihiro and colleagues expanded their transgenic animal studies to include BRAFV600E-driven cancer models, in collaboration with Prof. Martin McMahon." (PMID 37144683, 2023). "The epidermal growth factor receptor (EGFR) and B-Raf proto-oncogene, serine/threonine kinase (BRAF) are both well-studied kinases that play crucial roles in cancer progression." (PMID 38138441, 2023). "An energy‐based, mechanistic model of MAPK signaling is developed to describe the network rewiring responsible for adaptive (non‐genetic) and genetic resistance to RAF and MEK inhibitors in BRAF‐mutant cancers." (PMID 36700386, 2023). "Their continued survival and proliferation when BRAF is inhibited or degraded suggests that they contain other activated oncogenic drivers, making them multi-driver cancer cells." (PMID 38136350, 2023). "Combining the BRAFi dabrafenib (TAFINLAR®) and the MEKi trametinib (MEKINIST®) is an effective dual BRAF/MEK inhibition for cancer therapy, and the U.S. Food and Drug Administration (FDA) has approved these drugs for mono- and combination-therapy." (PMID 37834284, 2023).
cancer (continued). "The RAS (KRAS, NRAS, HRAS)-RAF (ARAF, BRAF, RAF1)-MEK (MAP2K1/2)-ERK (MAPK1/3) pathway is altered in ~40% of all human cancers, mainly through oncogenic mutations in RAS (32%) and the downstream effector BRAF (~10%)." (PMID 37370689, 2023). "Drugs targeting activating BRAF mutations have transformed the prognosis and treatment of MAPK-pathway-induced cancers." (PMID 36831610, 2023). "Poorly differentiated histology (p = 0.002), high-TSR (p = 0.033), BRAF-mutation (p = 0.008) and MSI (p = 0.011) were identified as significant risk factors for cancer recurrence." (PMID 37344790, 2023). "In a range of human cancers activating mutations in receptor tyrosine kinases (RTKs), RAS, BRAF and more rarely CRAF and MEK1/2 results in de-regulated ERK1/2 activation that drives the acquisition and maintenance of key cancer hallmarks." (PMID 37018014, 2023). "The study revealed a diverse set of cell responses to these perturbations, reflecting the varying roles of BRAF in oncogenesis, from serving as the sole driver in some mono-driver cancer cells to playing a complementary role in multi-driver cancer cells." (PMID 38136350, 2023). "For all analyzed methods (EU-TIRADS, BRAF, miRNAs), the ability to differentiate benign lesions and cancers as measured by the area under the ROC curve was higher for AUS-nuclear nodules than for AUS-other nodules." (PMID 37686562, 2023). "In the second sample, sent at timepoint 2 with disease progression, high level amplification of MET and BRAF was detected, suggesting potential selection of these alterations in the resistant cancer clone." (PMID 37147298, 2023). "The ROAR study is a prospective study focused on investigating a combined therapeutic strategy involving BRAF and MEK inhibitors for patients who have advanced rare cancers with the BRAFV600E mutation." (PMID 38001751, 2023). "In particular, BRAF V600E and TERT mutations are frequently reported in a subgroup of cancers with more aggressive clinicopathological behaviors." (PMID 37173884, 2023). "Mutational activation of BRAF, in a form of BRAFV600E, occurs in many human cancers, which is associated with the occurrence and development of human cancers." (PMID 37261210, 2023). "BRAF pV600E disease, as previously reported, was more common in cancer of the right colon, suggesting that right and left-sided colonic epithelium produce distinct CRC molecular phenotypes." (PMID 37350948, 2023). "Although relatively well characterized as BRAF mutant cancers, their poor response to current targeted therapy, difficult preneoplastic detection, and challenging endoscopic resection make the identification of their metabolic requirements a priority." (PMID 38092754, 2023). "The ROAR study demonstrated pan-cancer activity of the BRAF and MEK inhibitor combination in 21 histologies." (PMID 37059834, 2023). "First, BRAF degradation killed DU-4475 and Colo-205 cells via apoptosis but only partially inhibited the proliferation of other cancer cell lines." (PMID 38136350, 2023). "This set of highly variable kinases contains known cancer drivers and kinases with inhibitors already used in the clinic as cancer treatment, such as BRAF, AKT, MAP2K1, SRC among others." (PMID 36688815, 2023). "One of the most striking findings of these experiments is that the expression of endogenous R-RAS2Q72L is required for cancer cells that harbor concurrent mutations in key signaling elements of the RAS route, such as BRAF, RAF1 and PI3Kα." (PMID 36476833, 2023). "On the basis of pathway topology, it can be expected that this concept is also applicable to other cancers driven by highly active non-V600E BRAF mutants." (PMID 37656784, 2023).
cancer (continued). "In line with the paradoxical activation of the MAPK pathway by type I BRAF inhibitors, we found that the addition of encorafenib enhanced the effects of sotorasib withdrawal and converted withdrawal-resistant cancer cells to withdrawal-sensitive cancer cells." (PMID 37386628, 2023). "Gene mutations that resulted in the oncogenic activation of MAPK signalling pathway have been found to be indispensable in the pathogenesis of many cancers, including RET chromosomal rearrangement, BRAF and RAS point mutations." (PMID 37692064, 2023). "Dabrafenib is almost 20 times more specific for BRAF V600E mutants with respect to BRAF WT in multiple cancer cell lines with a lower IC50 in comparison with other BRAFi and displays inhibition in cell lines containing alternative oncogenic BRAF mutations." (PMID 37627054, 2023). "BRAF has the highest basal activity compared to ARAF and CRAF and is thus mutated most frequently in cancer." (PMID 38150000, 2023). "Specifically, somatic missense activating variants in the glycine-rich loop or the activation segment of the BRAF catalytic domain occur in about 7% of all cancers." (PMID 38067388, 2023). "Several preclinical and clinical studies have demonstrated that MAPK pathway inhibitors, such as inhibitors of BRAF and MEK, exhibit antitumor activity in cancers with BRAF mutations." (PMID 36856908, 2023). "BRAF K601E is a rarer mutation, with a low specificity to cancer (mostly follicular-variant PTC), thus carrying a relatively good prognosis compared to BRAF V600E mutation." (PMID 37374164, 2023). "In the context of cancer therapy, a possible mechanism of apoptosis induction by combined BRAF and MEK inhibitors treatments was proposed by our group." (PMID 38067230, 2023). "Our results have demonstrated that targeting BRAF V600E mutation, apatinib appears to be effective and safe for treating NSCLC and possibly other cancers with the same mutation." (PMID 36759818, 2023). "While the kinase-dependent role of CRAF in the ERK-MAPK signaling pathway parallels that of BRAF, its kinase-independent function in oncogenic-driven cancers garners special attention." (PMID 38111008, 2023). "We also discuss multiple non-melanoma cancer studies showing evidence of the actionability of BRAF beyond anchor type cancers." (PMID 37059834, 2023). "Da released from SPNs/Da/Dox can specifically inhibit BRAF V600E mutant cancer cells because it inhibits the MAPK signaling pathway by reducing the cytoplasmic level of ERK phosphorylation (p-ERK)." (PMID 37153748, 2023). "ZEB1 associates with poorer survival in most carcinomas, including CRCs; however, the role of ZEB1 in BRAF-mutant CRCs or a potential differential role of ZEB1 in CRCs based on the mutational status have not been explored." (PMID 37870961, 2023). "From a molecular point of view, poorly differentiated carcinomas defined by the Turin consensus harbor more frequently RAS mutations, while MSKCC cases are enriched with BRAF mutations; 40–55% of tumors harbor TERT promoter mutations." (PMID 36964880, 2023). "In our study, a total of four patients with HT experienced disease recurrence (N = 4/43, 9.3% of all patients with recurrence), with only a single patient (N = 1/43, 2.3% of all patients with recurrence) having HT and a BRAF-wild type carcinoma." (PMID 37190300, 2023). "Though having not been permitted, many clinical trials have proven efficacy of BRAF or MEK inhibitors or BRAF plus MEK inhibitors in more cancer types." (PMID 36254250, 2022). "A systematic review of the literature was performed to identify all BRAF gene alterations in cancer for which the corresponding functional class was reported." (PMID 35884534, 2022).
cancer (continued). "BRAF, or v-raf murine sarcoma viral oncogene homolog B, is well-characterized in a variety of cancers to be a driver of cancer progression." (PMID 35409289, 2022). "Some cancer types have a higher BRAF alternation frequency and its abnormal expression is associated with prognosis." (PMID 35910024, 2022). "The BRAF-MAPK signaling pathway correlates with the production of various immunosuppressive factors in regulating cancer-immune evasion." (PMID 35344507, 2022). "In late-stage cancers, NNMT mRNA expression also appeared to be increased in BRAF mutated cancers relative to BRAF wild type, although the difference was not statistically significant." (PMID 35177765, 2022). "Previous studies have shown that Navitoclax synergize effectively with targeted therapies such as EGFR inhibitors in NSCLC and MEK inhibitors in KRAS mutant cancers and BRAF mutant melanoma." (PMID 35256598, 2022). "Notably, most BRAF-mutated cancers with “very high” TIL/Tc infiltration in the TCGA cohort had stage I or IIA, only one patient had stage IIIC, and none was metastatic, so the hypothesis that an advanced clinical stage could drive the worst prognosis is unlikely." (PMID 36497365, 2022). "Understanding the role of lipid signaling in cancer progression for BRAF-driven cancer cells is important for diagnosis, treatment, and improving patient outcomes." (PMID 35565240, 2022). "BRAF and CTNNB1, two oncogenes frequently mutated in childhood cancers, showed higher mutation rates in AYAs." (PMID 36433963, 2022). "i3 cancers had more frequent KRAS, PIK3CA and BRAF mutations, including mutations known to be associated with more prominent MAPK pathway upregulation." (PMID 35773407, 2022). "Herein, we first report a systematic review of the literature aiming to identify all BRAF gene alterations belonging to a defined functional class across different cancer types." (PMID 35884534, 2022). "An overall assessment of the performance of the pan-cancer samples for all the source materials tested in this study was a maximum of 100% for BRAF; 98% for KRAS, and 94% for the GeneFusion Assays." (PMID 36293374, 2022). "Beyond their clinical relevance, the development of these anti-cancer agents contributed to the further understanding of BRAF physiological regulation." (PMID 35955671, 2022). "BRAF V600 class 1 mutations were only observed in i3 cancers and KRAS exon 3 mutations were enriched amongst i3 cancers." (PMID 35773407, 2022). "The frequency of activating RAF1 mutations in human cancers is much lower, because RAF1 has a lower basal kinase activity than BRAF." (PMID 35203304, 2022). "The results showed that there was a positive correlation between BRAF mRNA expression and CNVs in pan-cancer (r = 0.1716, p < 0.0001)." (PMID 35910024, 2022). "Mutation in BRAF V600E and loss of PTEN have been shown to recruit fibroblasts to the cancer microenvironment." (PMID 36242015, 2022). "The study of other regulatory mechanisms of BRAF V600E will help to develop better drugs to treat BRAF V600E positive cancer." (PMID 35748101, 2022). "In this study, we determine that DU-4475 is a mono-driver cancer cell line relying on BRAF and the mitogen-activated protein kinase pathway for viability and proliferation." (PMID 36011019, 2022). "The results demonstrated that DU-4475 cells, as mono-driver cancer cells, can be blocked and killed by BRAF or Mek inhibitors." (PMID 36011019, 2022). "Accordingly, Chapuy and colleagues identified BRAF (6% incidence), KRAS (3%) and MAP2K1 (3%) among candidate cancer genes, and mutations in these genes were mostly clonal." (PMID 35158933, 2022).